AKR1B10 (aldo-keto reductase family 1 member B10)
Diseases named in the same sentence as AKR1B10 in open-access papers (continued):
Sharing a sentence is not in itself a finding about the gene and the disease.
breast carcinoma (continued). "In vivo tumor xenograft experiments confirmed that AKR1B10 promoted breast cancer growth in mice." (PMID 34419144, 2021). "AKR1B10 may support breast cancer cell survival by releasing carbonyl stress and promoting fatty acid/lipid synthesis." (PMID 34063865, 2021). "AKR1B10 also plays a critical role in invasion and chemoresistance in breast cancer cells." (PMID 34419144, 2021). "AKR1B10 may thus promote breast cancer progression by activating the PI3K/AKT/NF-κB signaling cascade." (PMID 34419144, 2021). "Consistent with these published data, western blot and RTqPCR analysis of a smaller panel of breast cancer cell lines revealed low levels of AKR1B10 protein and mRNA in the ER+ ZR75.1 and MCF7 lines and high levels in the basal-like BT20, MDA-MB-468 and HCC1395 lines." (PMID 31221959, 2019). "Again, high expression of AKR1B10 (upper quartile) was significantly associated with reduced distant metastasis-free survival in ER−, but not ER+, breast cancer patients." (PMID 31221959, 2019). "Our results show that AKR1B10, as a new critical factor in breast cancer invasion and migration, may be a potential target for metastatic intervention." (PMID 28402270, 2017). "The discovery defines the role of AKR1B10 in the growth and progression of breast cancer." (PMID 28402270, 2017). "Protein levels of AKR1B10 was examined in 131 breast cancer specimens by immunochemistry." (PMID 28402270, 2017). "AKR1B10 is upregulated in human breast cancer and correlates with lymph node metastasis." (PMID 27248472, 2016). "However, an RNA-mediated knockdown study has indicated that AKR1B10 is an important regulator of fatty acid biosynthesis in human RAO-3 breast cancer cells." (PMID 27562730, 2016). "Ectopic expression of AKR1B10 in breast cancer cells MCF-7 and MDA-MB-231 or siRNA-mediated silencing in BT-20 cells affected cell adhesion, migration and invasion in cell culture, and metastasis to the lung in the nude mice through upregulation of integrin α5 and δ-catenin." (PMID 27248472, 2016). "AKR1B10 upregulated integrin α5, δ-catenin and fibronectin in breast cancer cells." (PMID 27248472, 2016). "This study characterized the molecular mechanisms of AKR1B10-promoted breast cancer metastasis." (PMID 27248472, 2016). "AKR1B10 is overexpressed in colorectal, uterine, breast cancers." (PMID 22937096, 2012). "Several findings also support the hypothesis that AKR1B10 may be a useful marker for differentiation and proliferation of liver, colon, lung and breast cancer." (PMID 23071592, 2012). "Studies have shown that proliferation of cancer cells largely relies on proliferation-related proteins including c-myc, Survivin and cyclinD1, which prompted us to investigate whether these regulators were involved in AKR1B10-induced proliferation of breast cancer cells." (PMID 34419144, 2021). "However, the molecular mechanism of AKR1B10 promoting FAO in breast cancer metastasis via PPARGC1A remains unclear." (PMID 34217300, 2021). "Thus, AKR1B10 might serve as a new prognostic indicator and a potential therapeutic target for breast cancer." (PMID 34419144, 2021). "Breast cancer RAO-3 cells exhibit elevated AKR1B10 expression, and the high expression is observed in situ and in the serum of the patients, suggesting that AKR1B10 expression may be a diagnostic and therapeutic marker as well as a poor prognostic factor for breast cancer." (PMID 34063865, 2021). "In breast cancer cells, AKR1B10 was associated with acetyl-CoA carboxylase alpha (ACCA), the rate-limiting enzyme of de novo long chain fatty acid synthesis, and knockdown of AKR1B10 in cancer cells led to a significant reduction in both ACCA protein levels and fatty acid synthesis." (PMID 30959792, 2019). "However, the molecular mechanisms of AKR1B10 promoting the metastasis of breast cancer remain largely unknown." (PMID 28402270, 2017).
breast carcinoma (continued). "While AKR1B10 promotes tumorigenesis in HCC, breast cancer, lung cancer, and pancreatic cancer, we demonstrate that its expression predicts better prognosis in gastrointestinal cancers, based on analyses of public databases and patient samples from FAH-SYSU." (PMID 40845116, 2025). "Growing evidence supports that AKR1B10 is involved in the occurrence and progression of many cancers, such as HCC, breast cancer, non-small cell lung cancer, and pancreatic cancer." (PMID 36845547, 2023). "In fact, AKR1B10 activates diacylglycerol (DAG)-mediated PKC/ERK signaling in breast cancer cells and promotes breast cancer metastasis via an integrin α5 and δ-catenin mediated mechanism." (PMID 35280770, 2022). "It has been recently reported that AKR1B10, another member of the aldo-keto family reductases, promotes the metabolic shift from glycolysis towards FAO, supporting the metastasis of breast cancer cells." (PMID 36451864, 2022). "In breast cancer RAO-3 cells, AKR1B10 interacts with acetyl-CoA carboxylase-α (a rate-limiting enzyme of de novo fatty acid synthesis), preventing acetyl-CoA carboxylase-α ubiquitination and proteolysis, and thereby promoting fatty acid/lipid synthesis." (PMID 34063865, 2021). "Breast cancer cell lines overexpressing AKR1B10 (MCF-7/AKR1B10) and breast cancer cell lines with knockdown of AKR1B10 (BT-20/shAKR1B10) were constructed to analyze the impact of AKR1B10 expression on cell proliferation and migration of breast cancer." (PMID 34419144, 2021). "Previous studies reported that AKR1B10 increased the synthesis of the lipid second messengers PIP2 and DAG in breast cancer cells, activating the Raf/MEK/ERK signalling pathway and promoting cancer cell proliferation." (PMID 32547320, 2020). "The data presented here demonstrates that AKR1B10 expression is elevated in ER− and HER2+ breast cancers and that within these breast cancer subtypes, high AKR1B10 expression is associated with an increased incidence of metastatic relapse at secondary sites." (PMID 31221959, 2019). "So AKR1B10 not only is overexpressed in breast cancer, but also promotes the migration and invasion of MCF-7 cells by up-regulation AKR1B10 expression via the ERK signaling way in MCF-7 cells." (PMID 28402270, 2017). "However, the mechanisms of AKR1B10 promoting tumorigenesis in breast cancer remain unclear." (PMID 28402270, 2017). "AKR1B10 expression was significantly greater in breast cancer tissue compared to paired non-cancerous tissue." (PMID 34419144, 2021). "AKR1B10 promotes the proliferation, migration and invasion of breast cancer cells via the PI3K/AKT/NF-κB signaling pathway and represents a novel prognostic indicator as well as a potential therapeutic target in breast cancer." (PMID 34419144, 2021). "Cytosolic AKR1B10 is secreted from cells through a lysosome-mediated nonclassical pathway, increasing its presence in breast cancer patients’ serum." (PMID 34063865, 2021). "AKR1B10 overexpression elevated the levels of phosphorylated-PI3K and phosphorylated-AKT, and not surprisingly, inhibition of AKR1B10 decreased the levels of these molecules in breast cancer cells." (PMID 34419144, 2021). "In macrophages, AKR1B10 is secreted through lysosomes through a non-classical pathway, increasing its level in the serum of patients with breast cancer." (PMID 30320113, 2018). "Our previous studies have shown that AKR1B10 is secreted through a lysosome-mediated non-classical pathway, which leads to the increase of AKR1B10 in the serum of breast cancer patients." (PMID 28402270, 2017). "AKR1B10 is upregulated in multiple human tumors, including liver, lung, and breast cancers, functioning as a potential negative prognostic factor." (PMID 27248472, 2016). "AKR1B10 was the first AKR1B protein which was demonstrated to enhance cell proliferation and promote cell survival through its ability to interact with and stabilize ACCA in breast cancer cells and in colon cancer cells." (PMID 22876234, 2012).
breast carcinoma (continued). "AKR1B10, as a critical onco-protein, may activate the PI3K/AKT/NF-κB signaling cascade to promote the expression of proliferation-related and EMT-related proteins and consequently stimulate proliferation, migration and invasion in breast cancer cells." (PMID 34419144, 2021). "Furthermore, immunohistochemistry (IHC) was used to examine AKR1B10 expression in 30 breast cancer samples and paired adjacent non-tumor tissue." (PMID 34419144, 2021).
lung carcinoma (33 papers, 2013 to 2025). "This is in line with our observations of the clinicopathological analysis using datasets from the GPL570 platform, TCGA, and Kaplan–Meier that advocated the significant association of the AKR1B10 expression with the disease progression of lung cancer." (PMID 39001490, 2024). "Cyclins A, D, and E have long been associated with lung cancer progression; nonetheless, very little regarding its correlation to chemoresistance regulated by AKR1B10 has been uncovered." (PMID 39001490, 2024). "AKR1B10 is also frequently overexpressed in interstitial pneumonia, a disease that increases the risk of lung cancer in smokers." (PMID 34063865, 2021). "Regardless, by performing a systematic analysis of publicly available data from transcriptomic studies of lung tissue and cells, our study provides strong evidence to support a potential role of AKR1B10 in smoking-associated lung cancer." (PMID 32097409, 2020). "The human AKR1B10 was shown to be associated with several types of cancers including lung cancer and liver cancer." (PMID 25887478, 2015). "In addition, increased AKR1B10 expression is associated with smoking in patients with lung cancer and has been proposed to be a potential biomarker for smoking-induced lung cancer." (PMID 24391771, 2013). "Moreover, AKR1B10 has been considered a potential biomarker of CS-associated lung cancer." (PMID 33660061, 2021). "For example, high expression of AKR1B10 in lung cancer brain metastases enhanced the Warburg effect and promoted glycolysis, leading to resistance to pemetrexed (PEM)." (PMID 40166469, 2025). "In lung cancer brain metastases, high expression of AKR1B10 promoted glycolysis and lactate production, leading to a significant increase in the level of H4K12 lactylation." (PMID 40166469, 2025). "In brain metastases of lung cancer, AKR1B10 upregulates H3K18 lactylation, suppresses LDHA expression, and induces resistance to PEM." (PMID 40843350, 2025). "Recent studies have indicated that AKR1B10 can promote histone lactylation, leading to the development of resistance in brain metastatic cells originating from lung cancer." (PMID 40703521, 2025). "The AKR inhibitor, ponalrestat (statil) is reported to inhibit cancer cachexia by suppressing IL-1 expression Ponalrestat was found to suppress the proliferation of breast and lung cancer cells by downregulating the expression of AKR1B10." (PMID 39055885, 2024). "This study positions AKR1B10 as a potential therapeutic target, offering a new avenue to improve lung cancer treatment outcomes by mitigating the adverse effects of sublethal chemotherapy." (PMID 39001490, 2024). "Our analysis revealed a significant upregulation of AKR1B10 in response to taxol and doxorubicin treatment, correlating with poor survival rates in lung cancer patients." (PMID 39001490, 2024). "Here we identified an opposing role of AKR1B10 in lung cancer derived brain metastatic cells that AKR1B10 presents a facilitative effect on anaerobic glycolysis." (PMID 37587486, 2023). "Overall, these results demonstrate the robustness of AKR1B10 and CEACAM5 in the cytologically normal bronchial epithelium in discriminating both the high-risk and lung cancer groups from the low-risk group." (PMID 37760474, 2023). "In general, these data suggested that AKR1B10 remarkably facilitates the Warburg effect in lung cancer BM cells." (PMID 37587486, 2023). "Noteworthy, AKR1B10 has been demonstrated to be significantly overexpressed in a lung cancer cell line with high BM potential and NSCLC patients with BM in our previous work." (PMID 37587486, 2023). "AKR1B10 silencing resulted in caspase-3-mediated apoptosis of colon carcinoma cells and lung carcinoma cells." (PMID 36028503, 2022). "Its treatment of A549 cells induces the expression of AKR1B10 through ROS- and Nrf2-dependent mechanisms, leading to further progression of malignant lung cancer cells through activating the ERK pathway." (PMID 34063865, 2021).
lung carcinoma (continued). "As a member of aldehyde ketone reductase superfamily, AKR1B10 was first studied in the oncogenic mechanisms of lung cancer." (PMID 34419144, 2021). "Studies have found that AKR1B10 is highly expressed in liver cancer, breast cancer, lung cancer and other tumor tissues." (PMID 34027794, 2021). "A considerable body of evidence indicates that AKR1B10 participates in the occurrence and development multiple cancer, such as nasopharyngeal carcinoma, lung cancer and colorectal cancer." (PMID 34027794, 2021). "The systematic analysis of transcriptomic studies performed here revealed a potential critical link between AKR1B10 expression, smoking and occurrence of lung cancer." (PMID 32097409, 2020). "Nevertheless, these findings are important because they have identified AKR1B10 as a biomarker which expression is triggered by cigarette smoking and can be simultaneously observed in lung cancer specimens." (PMID 32097409, 2020). "For example, CYP24A1 has oncogenic properties in lung adenocarcinoma and AKR1B10 has been shown to induce the metastatic potential of lung cancer cells to the brain in vitro." (PMID 33255394, 2020). "Consistently, the NRF2 target gene, aldose ketose reductase family 1 member B10 (AKR1B10), was also reported as a reliable biomarker for smoking in lung cancers, and its expression is a good surrogate for NRF2 activation in lung cancer." (PMID 30150714, 2018). "Moreover, AKR1B10 inhibitors significantly inhibit the metastasis and invasion abilities of cisplatin-resistant lung cancer cells." (PMID 39001490, 2024). "In addition, AKR1B10 is shown to be greatly elevated in the brain metastasis of lung cancer and the expression in the serum of lung cancer patients with bone metastasis, which serves as a novel diagnostic biomarker." (PMID 39001490, 2024). "We investigated whether the glycolysis is essential for the AKR1B10-mediated obtainment of PEM resistance in lung cancer BM cells." (PMID 37587486, 2023). "In the univariate analysis, compared to the low-risk group, AKR1B10, ALDH3A1, CEACAM5, and IDH2 are higher than the high-risk or cancer group, i.e., their upregulation discriminates the low-risk group from the high-risk group as well as the lung cancer group." (PMID 37760474, 2023). "Aldo-keto reductase family 1 B10 (AKR1B10) was recently found to be elevated in lung cancer BM." (PMID 37587486, 2023). "An antioxidant (ethoxyquin) induces AKR1B10 expression in lung cancer cell lines A549 and H23." (PMID 34063865, 2021). "Moreover, AKR1B10 expression was relatively higher in lung cancer specimens compared to matched healthy tissue obtained from nonsmoking individuals." (PMID 32097409, 2020). "Although AKR1B10 is downregulated in gastrointestinal cancers and inflammatory bowel diseases, it is later found to be differentially upregulated and proposed as a prognostic biomarker in numbers of other cancer types, such as nasopharyngeal carcinoma, breast, pancreatic, and lung cancers." (PMID 39001490, 2024). "Therefore, AKR1B10 is upregulated in breast and lung cancers and promotes tumor progression and worse prognosis; and AKR1B10 may play a tissue-specific role in the tumorigenesis and cancer progression." (PMID 38370384, 2024). "In summary, the present study reveals that elevated AKR1B10 enhances glycolysis through regulation of LDHA and the resulting elevated lactate promotes transcriptional activation of the cell cycle-related gene CCNB1 by histone lactylation, inhibiting the susceptibility of lung cancer BM cells to PEM." (PMID 37587486, 2023). "However, whether there is any association between elevated AKR1B10 expression and poor PEM drug response in lung cancer BM is unknown." (PMID 37587486, 2023). "Thus, AKR1B10 is a diagnostic marker of NSCLC in smokers, as its smoking-induced upregulation may be an early indicator among the multiple events leading to lung cancer." (PMID 34063865, 2021).
lung carcinoma (continued). "Thus, there is strong evidence to suggest that cigarette smoking-induced upregulation of AKR1B10 may represent an initial critical step in the cascade of events leading to lung cancer." (PMID 32097409, 2020). "Alternatively, AKR1B10 may promote lung cancer via its enzymatic activity that inhibits the conversion of ß-carotene to retinoic acid and promotes the conversion of highly reactive aldehyde and ketone groups into hydroxyl groups in neoplastic cells resulting in an inhibition of apoptosis." (PMID 24391771, 2013). "The lung cancer brain metastatic subpopulation cells (PC9-BrM3) exhibited significant resistance to PEM and silencing AKR1B10 in PC9-BrM3 increased the PEM sensitivity in vitro and in vivo." (PMID 37587486, 2023). "A number of AKR1B10 inhibitors have been developed, of which HCCFA, the most potent, significantly inhibits not only the migration, proliferation, and metastasis of lung cancer A549 cells, but also the metastatic and invasive abilities of cisplatin-resistant A549 cells." (PMID 34063865, 2021). "In general, AKR1B10 mRNA down-regulated in most of gastrointestinal cancer, genitourinary cancer and PCPG, but up-regulated in most of developmental gastrointestinal cancer, some of gynecological cancer, glioma and lung cancer when compared with normal tissues from TCGA databases." (PMID 39712017, 2024). "Surprisingly, the most potent lead, VC59, did not bind to AKR1B10 in living lung cancer cells." (PMID 34940623, 2021). "Finally, our findings indicate that AKR1B10 is overexpressed in lungs of healthy people who smoke but had no cancer as well as in lung carcinoma from non-smokers." (PMID 32097409, 2020).